POLD1 (DNA polymerase delta 1, catalytic subunit)
Diseases named in the same sentence as POLD1 in open-access papers (continued):
Sharing a sentence is not in itself a finding about the gene and the disease.
tumor (continued). "We further analyzed the relationship between POLD1 expression and the clinical characteristics of ccRCC patients, revealing that POLD1 expression was significantly associated with pathologic tumor stage and histologic grade." (PMID 37047824, 2023). "For example, the upregulation of POLD1 in breast and liver cancer is correlated with higher tumor mutation burden and poor prognosis." (PMID 37047824, 2023). "Multivariate Cox regression analysis after adjustment for MSI status and tumor type showed that POLE/POLD1 is an independent risk factor for immunotherapy benefit." (PMID 35780178, 2022). "On the contrary, the literature data suggest that high tumor mutational burden is characteristic for tumors with defects in POLE/POLD1 genes." (PMID 35562977, 2022). "POLE/POLD1 mutations are not only closely related to tumor formation, but are also a potential molecular marker for predicting the efficacy of immunotherapy in pan-carcinomatous species." (PMID 35780178, 2022). "The single positive tumor exhibited high mutational burden (93.7 mutations/megabase (Mb)) and was found to harbor a germline potentially pathogenic variant in POLD1 (c.1225C>T p.R409W)." (PMID 35668106, 2022). "Results indicate that tumorigenesis is initiated by MMRd and the inherited POLD1 PV contributes to fast tumor progression reflected by an ultra-high tumor mutational burden (TMB) and specific mutational signatures." (PMID 36291559, 2022). "One tumour had a POLD1 (p.Leu227Pro) mutation, with a TMB of 206.26 mutations/Mb, and the second had a POLE1 (p.Pro286Arg) mutation, with a TMB of 577.91 mutations/Mb." (PMID 33632293, 2021). "The sample size used to assess DC in this study was considerably small for determining the significance of TERT and POLD1 mutations for tumor cell dedifferentiation in EC." (PMID 35002543, 2021). "We identified a significant association between elevated POLD1 expression and poor patient survival and immune-excluded tumor microenvironment of HCC." (PMID 34868924, 2021). "Occasionally, defective MMR protein expression in tumor tissue can be secondary to germline or somatic mutation in another DNA repair or replication-associated gene, such as POLD1/E or less frequently, MUTYH." (PMID 32660107, 2020). "POLE/POLD1 gene variants have been suggested as potential markers for immunotherapy due to their significant association with the tumor mutational burden (TMB), an effective indicator for response prediction in immunotherapy." (PMID 31673068, 2019). "A recent study has shown that germline missense mutations of POLE and POLD1 genes lead to development of polymerase proofreading-associated polyposis, which is similar to LS with regards to tumor spectrum, including an increased risk of ECs." (PMID 31866764, 2019). "Tumors with MSI-H or mutations in POLE or POLD1 genes, which carry an extraordinarily excessive number of somatic genetic events, compose only a small proportion of human neoplasms." (PMID 30211169, 2018). "Variants in POLE and POLD1 are known to increase the somatic mutation rate in tumours, thereby increasing the risk of tumour development." (PMID 28331556, 2017). "Data from mice with homozygous germline Pole and/or Pold1 mutations at the exonuclease active site were shown to have distinct, but overlapping tissue-specific tumor phenotypes." (PMID 24583393, 2014). "The presence of PVs in POLE and POLD1 affecting the exonuclease activity of polymerases ε and δ, respectively, causes uncorrected errors during DNA replication resulting in the highest tumour mutational burden, often exceeding 100 mut/Mb, and referred to as ultra-hypermutator phenotype." (PMID 40237887, 2025). "POLD1 mutations can lead to higher tumor mutation load, positive for immunotherapy." (PMID 41585239, 2025). "Other promising markers include POLE/POLD1 mutation and tumor-infiltrating lymphocytes (TILs)." (PMID 41294832, 2025).
tumor (continued). "POLE and POLD1 genes encode the catalytic subunits of DNA polymerase ε and δ, respectively, which play an important role in DNA replication and correction, and their mutations directly affect the occurrence and development of tumours." (PMID 39530091, 2024). "However, a study that used CRISPR to separately engineer different POLE and POLD1 mutations into two different mouse tumor cell lines found that ICI sensitivity was significantly improved in those syngeneic POLE and POLD1 tumors." (PMID 37388540, 2023). "Also, the mutational signatures associated with POLE/POLD1 exonuclease domain defects have been reproduced in vitro in tumor PDOs with a POLE hotspot mutation, POLE CRISPR-edited cells and POLD1 patient-derived fibroblasts." (PMID 36756361, 2023). "However, while POLE/POLD1-mutated CRCs share some features with MSI-H CRCs (such as a high tumor mutation burden), they are typically MSS tumors and are unlikely to account for any of the sporadic MSI-H EOCRC cases in our meta-analysis." (PMID 39132649, 2023). "Thus, the function of POLE and POLD1 is essential to suppress gene mutations and consequently tumor genesis." (PMID 37108738, 2023). "The observed mutational signature pattern in our patient tumor tissue is in keeping with the expected loss of exonuclease activity of POLD1 and supports our hypothesis that p.D402N negatively impacts the DNA proofreading function." (PMID 38067377, 2023). "Moreover, diversified POLD1 expression profiles have been reported in association with clinicopathological features in a variety of tumor types." (PMID 36980791, 2023). "Additionally, POLD1 mRNA expression was significantly associated with tumor mutation burden, microsatellite instability, and prognosis in various tumors." (PMID 35189839, 2022). "However, an analysis of tumours from children with biallelic germline MMR deficiency demonstrated a subset of tumours with remarkably high mutation burdens (>250 mutations/Mb) that also had a somatic mutation in POLE or POLD1." (PMID 36010882, 2022). "The current analysis showed that the POLE mutation may be through the MMR, TGF-β, and RTK/RAS/RAF signaling pathways affecting tumor development, while the POLD1 mutation may affect tumor development through the MMR signaling pathway." (PMID 35780178, 2022). "Previous studies have suggested that POLD1 may be associated with the malignant survival of tumor cells and that POLD1 is generally highly expressed in BRCA tissues." (PMID 33747905, 2021). "Here, we sequenced normal tissue and tumor DNA from individuals with germline POLE/POLD1 mutations." (PMID 34594041, 2021). "Another point against a classical tumor suppressor model is the fact that only a minority of tumors with POLE or POLD1 EDMs show LOH or other inactivating mutations that could act as ‘second hits’." (PMID 24583393, 2014). "POLE p.Leu424Val, POLD1 p.Ser478Asn, and POLD1 p.Pro327Leu all map within the proofreading (exonuclease) domain of the respective enzyme, suggesting that deficient proofreading repair during DNA replication is the cause of our patients' tumours." (PMID 23447401, 2013). "Hence, only a small proportion of high tumor mutation burden samples with SBS20 signatures may be attributed to POLD1 mutations and thus, there may be other mutagenesis forces for SBS20 in GC, particularly for tumors from Asia." (PMID 39350044, 2024). "Furthermore, POLE/POLD1-mutated tumors show a high tumor mutational burden, and the identification of these genetic alterations could be used to select patients who are suitable for immunotherapy treatment." (PMID 39684352, 2024). "However, the underlying mechanisms of POLD1 regarding tumor progression and the immune microenvironment in RCC remained unknown." (PMID 37047824, 2023).
tumor (continued). "Besides that, it was discovered that tumors with DNA polymerase epsilon (POLE)/POLD1 mutations had higher proportions of CD8+ tumor-infiltrating lymphocytes, indicating that patients with this kind may benefit more from immune checkpoint inhibitor therapy." (PMID 37105989, 2023). "Therefore, both germline and somatic POLD1 mutations triggering tumor formation may turn out to be biallelic." (PMID 36980791, 2023). "The upregulated expression of POLD1 may incur a greater risk of tumor advance in ccRCC patients." (PMID 37047824, 2023). "However, the underlying mechanisms of POLD1 concerning tumor progression and immune engagement in RCC remain unknown." (PMID 37047824, 2023). "Thus, we speculate that ZNF217 amplification and/or POLD1 mutations in the tumor may affect overall genome stability and lead to the generation of tumor-specific neoantigens and consequently extensive lymphocyte infiltration." (PMID 35912186, 2022). "Our POLD1-knockout model thus complements algorithm-based models to predict the pathogenicity of tumor-specific variants of unknown significance and illustrates a novel and potentially clinically relevant therapeutic approach using ATR/CHK1 inhibitors in POLD1-deficient tumors." (PMID 33144657, 2020). "One hypermutated ChRCC tumor with the POLE and POLD1 mutations displayed SBS26 and SBS44, reflective of dMMR." (PMID 41563788, 2026). "Clonal evolution model indicated early POLE/POLD1 events and survival of founding clone during tumor recurrence." (PMID 41797895, 2026). "Ultramutation is associated with a better prognosis and immunotherapy response, highlighting the need to define tumour POLE/POLD1 status unambiguously." (PMID 41263451, 2025). "Patients carrying mutations in these genes exhibit a highly distinctive phenotype leading clinicians to consider POLE and POLD1 testing not only based on the polyposis phenotype but also on the broader tumor spectrum." (PMID 39661238, 2025). "When proofreading deficiency co-exists with MMR deficiency, the tumour mutational spectra shift to SBS14 in the case of POLE mutations and SBS20 for POLD1." (PMID 40237887, 2025). "This paradox is resolved by the frequent occurrence of somatic LOH at the POLD1 locus in tumor tissue." (PMID 40661943, 2025). "A molecular characteristic of such cells is that they require HDAC10 to maintain the expression of MYC and POLD1 (i.e., HDAC10ness in analogy to the BRCAness of certain tumor cells)." (PMID 40301616, 2025). "Research indicates that POLE and POLD1 mutations are linked to a higher TMB, which can potentially enhance the tumor’s visibility to the immune system, thereby improving the response to ICIs." (PMID 40575168, 2025). "In these ultra-hypermuted tumor cases, a secondary somatic event such as an inactivating mutation in POLE or POLD1 genes is considered to be responsible for the mutation burst(s) leading to the ultra-hypermutated phenotype." (PMID 39233831, 2024). "Our analyses of mutations with VAF higher than the one of the POLE/POLD1 mutations and of potential driver genes point towards alterations that could represent new targets whether they occur early during oncogenesis or are selected during the evolution of the tumor." (PMID 39233831, 2024). "The defective MMR protein expression in tumor tissue can be attributable to germline or somatic mutation in another DNA repair or replication-associated gene, such as BRAF, POLE/POLD1, or less frequently, MUTYH." (PMID 38297350, 2024). "In this work, we first confirmed by qPCR analysis that DFO treatment significantly reduced the mRNA expression of POLD1 in tumor colonoids." (PMID 36703617, 2023).
tumor (continued). "The final results pinpointed the vital role of the POLD1 gene in the prognosis of ccRCC and illustrated a relevance between POLD1 expression and the clinical outcome of the ccRCC cohort as well as the tumor-infiltrating immune cells." (PMID 37047824, 2023). "In conjunction with these results, POLD1 played a crucial function in recruiting and modulating TILs in ccRCC; and the molecular mechanism and function of POLD1 in regulating the tumor microenvironment also pinpoints the direction for our future research." (PMID 37047824, 2023). "Gut microorganisms, genetic mutations like POLE/POLD1 and NOTCH4, tumor lymphoid infiltrating cells (TILs), and other novel biomarkers have the potential to develop into new predictors." (PMID 37190201, 2023). "Our enrichment analysis results showed that POLD1 is closely related to immunity-related characteristics, especially anti-tumor immune response regulation." (PMID 37047824, 2023). "For instance, dMMR/MSI-H CRC patients with low TMB, immunosuppressive tumor microenvironment, or mutation in the PTEN gene or PIK3CA gene are resistant to ICIs, while pMMR/MSS CRC patients with a mutation in POLE or POLD1 gene are sensitive to ICIs." (PMID 37441082, 2023). "Next, to further explore the composition of 22 immune cells in the ccRCC tumor immune microenvironment (TME) in different POLD1 gene levels, the CIBERSORT algorithm was applied to dissect the TME of ccRCC patients (POLD1high vs. POLD1low groups)." (PMID 37047824, 2023). "TIMER and TISIDB databases were utilized to comprehensively investigate the potential relevance between the POLD1 levels and the status of the immune cells, as well as the tumor infiltration of immune cells." (PMID 37047824, 2023). "Together, our data reveal that TFRC depletion in colon epithelial cells can lead to decreased cellular iron levels, reduced POLD1 expression, increased apoptosis, and repressed tumor growth." (PMID 36703617, 2023). "Like iron chelation and TFRC disruption, POLD1 reduction caused increased DNA replication stress, DNA damage response (DDR), apoptosis and repressed tumor growth." (PMID 36703617, 2023). "To further explore the mechanisms through which POLD1 regulates the ccRCC anti-tumor immune response, we detected the impact of POLD1 on several oncogenic signaling pathways using a Western blot." (PMID 37047824, 2023). "Current evidence suggests that liver cancer patients with high levels of POLD1 tend to form an inhibitory tumor microenvironment and tend to lead to tumor progression." (PMID 37105989, 2023). "Among DNA repair genes, we detected evidence of positive selection in the tumor suppressor-encoding PALB2 and in four DNA polymerase-encoding genes (POLA1, POLD1, POLK, and POLM)." (PMID 37728212, 2023). "Current studies of POLD1 focus on its hypermutation’s effects on tumor immune microenvironments, and it has the potential as a biomarker to track the effectiveness of immunotherapy." (PMID 37105989, 2023). "In contrast, heterozygous exonuclease mutations in POLD1 and POLE are readily detected by sequencing tumor or germline DNA." (PMID 36291559, 2022). "NTRK‐positive CRC tumors demonstrated very high tumor mutation burden (median 53 mut/MB), microsatellite instability‐high (MSI‐H, 76%), and an enrichment of concurrent POLE and POLD1 mutations." (PMID 35506567, 2022). "Functionally, in vivo orthotopic injection model showed that stable knockdown of POLD1 in HCC cells suppressed tumor incidence and tumorigenicity and had a trend of diminished lung metastasis." (PMID 35865168, 2022). "The most common tumour types were colorectal, followed by endometrial in POLD1 heterozygotes and duodenal in POLE heterozygotes." (PMID 33948826, 2022). "PPAP is caused by germline pathogenic variants in the exonuclease domains of POLD1 or POLE genes, and affected families have an increased risk for a number of tumours also prevalent in LS, in particular CRC and EC." (PMID 33499123, 2021).
tumor (continued). "Low-tumor grade and early-stage HCC patients tended to have reduced expression of POLD1, whereas high tumor grades and advanced stages were related to the increased POLD1 expression." (PMID 34868924, 2021). "This study first investigated the molecular and clinical role of the POLD family and revealed the significant relationship between elevated POLD1 expression and the poor survival and immune-excluded tumor microenvironment of HCC patients." (PMID 34868924, 2021). "The Sankey diagram shows the relationships between tumor grades, stages, POLD1 expression levels and survival." (PMID 34868924, 2021). "Our study has demonstrated a link between elevated POLD1 expression and patient survival and the tumor microenvironment in HCC." (PMID 34868924, 2021). "We consider tumor sequence analysis of utmost importance for a proper classification of POLE and POLD1 ED variants." (PMID 32792570, 2020). "Based on that, 9 out of the identified 14 candidate genes passed our criteria, i.e., showed a highly significant (i.e., p < 0.001) association with their gene expression in one or more tumor entities like PER1 and POLD1." (PMID 29445424, 2018). "As was the case for CRCs, POLD1 EDMs were very rare common, seen in just one tumour in each cohort (approximately 0.5%)." (PMID 23447401, 2013). "The tumor spectrum in PPAP also varies depending on the causal gene, POLD1 or POLE." (PMID 41487566, 2025). "In addition, POLE and POLD1 mutations are associated with defective DNA repair, resulting in hypermutated phenotypes characterized by high TMB and increased tumor-infiltrating lymphocytes (TILs)." (PMID 41019039, 2025). "While this pro-tumorigenic axis complicates prognosis, it also hints at combinatorial strategies: targeting MYC alongside ICIs could exploit POLD1-driven immunogenicity while curbing tumor growth." (PMID 40661943, 2025). "Some gene mutations, such as BRCA, ATM, and POLE/POLD1, are not conducive to the prognosis of tumour diseases but are beneficial to immunotherapy." (PMID 39530091, 2024). "Also a rare patient subgroup with mutations in polymerase ε (POLE) or δ1 (POLD1), associated with a hypermutated phenotype and mostly observed in microsatellite-stable (MSS)/MMR-proficient tumours, shows ICB responsiveness." (PMID 38664577, 2024). "This prospective clinical trial evaluated the anti-tumor effect of toripalimab in non-MSI-H patients with unselective POLE/POLD1 mutations." (PMID 39218995, 2024). "Notably, our study identifies POLD1 as a significant gene, with our experiments confirming its crucial role in predicting tumour invasion and prognosis in PCa patients." (PMID 38918844, 2024). "The POL VAF of patient SYSUCC07, who achieved partial response, did not change because the tumor harbored a POLD1 germline mutation." (PMID 39218995, 2024). "Moreover, an in vivo orthotopic liver injection model revealed that POLD1 knockdown in HCC cells diminished tumor incidence, size, and lung metastases in mice." (PMID 36980791, 2023). "Moreover, recent data suggested the occurrence of an abundance of tumor-infiltrating lymphocytes (TILs) in POLE/POLD1-mutant CRCs." (PMID 36980791, 2023). "Finally, although this study has demonstrated the potential role of POLD1 in tumor immune regulation and several oncogenic signaling pathways, the autophagy and ferroptosis signaling pathways are both complex processes." (PMID 37047824, 2023). "POLE/POLD1 mutant tumors are recognized by the immune system, making the tumor immunogenic." (PMID 37108738, 2023). "We analyzed mutational signatures from the POLD1/POLH tumor and the POLE tumor." (PMID 37095444, 2023).